CPT1B (carnitine palmitoyltransferase 1B)
Description:
Catalyzes the transfer of the acyl group of long-chain fatty acid-CoA conjugates onto carnitine, an essential step for the mitochondrial uptake of long-chain fatty acids and their subsequent beta-oxidation in the mitochondrion.
Synonyms: CPT1-M; CPTI-M; M-CPT1; CPT1M; CPTI; MCCPT1; MCPT1
Tractability: Small molecule: an approved drug acts on it; a high-quality ligand is known; it belongs to a druggable protein family. Antibody: UniProt predicts a signal peptide or a membrane-spanning region. PROTAC: a small molecule that binds it is known.
Target class: Group translocator; Transporter
Gene: Protein-coding gene on chromosome 22 (50,568,856 to 50,578,681, reverse strand). Ensembl gene ENSG00000205560.
Subcellular location: Mitochondrion outer membrane
Pathways (Reactome):
Metabolism: Carnitine shuttle
Gene Ontology:
Molecular function: carnitine O-palmitoyltransferase activity; protein binding; acyltransferase activity
Biological process: carnitine metabolic process; carnitine shuttle; fatty acid beta-oxidation; fatty acid metabolic process; long-chain fatty acid transport; response to blue light
Cellular component: mitochondrion; mitochondrial outer membrane; mitochondrial intermembrane space
Genetic constraint (gnomAD): Loss-of-function variants: 57 observed, 95.76 expected, observed/expected ratio (o/e) 0.6, 90% interval 0.48 to 0.74. The upper end of that interval is the gene's LOEUF score, 0.74, which puts it in group 3 of 6, group 1 being the genes least tolerant of losing a copy. Missense variants: 983 observed, 1,058.2 expected, observed/expected ratio (o/e) 0.93, 90% interval 0.88 to 0.98. Synonymous variants: 398 observed, 402.43 expected, observed/expected ratio (o/e) 0.99, 90% interval 0.91 to 1.08.
Gene-disease validity (ClinGen):
ClinGen rates the evidence that CPT1B causes each of these diseases.
inherited fatty acid metabolism disorder (inheritance undetermined): No Known Disease Relationship. A group of genetic disorders that result from the inability to produce or use an enzyme required to oxidize fatty acids, resulting in an inability to generate energy from fatty acid sources.
Homologues: Orthologues: chimpanzee CPT1B (99% identical), guinea pig CPT1B (91% identical), dog CPT1B (91% identical), macaque CPT1B (89% identical), mouse Cpt1b (87% identical), rat Cpt1b (86% identical), pig CPT1B (85% identical), tropical clawed frog cpt1b (65% identical), zebrafish cpt1b (64% identical), rabbit CPT1B (53% identical), Drosophila melanogaster whd (51% identical), Caenorhabditis elegans cpt-1 (44% identical), and 1 more. Paralogues in human: CPT1A (63% identical), CPT1C (53% identical), CRAT (26% identical), CHAT (24% identical), CPT2 (24% identical), CROT (22% identical).
Diseases named in the same sentence as CPT1B in open-access papers:
CPT1B is named in the same sentence as 84 diseases in open-access papers, as found by Europe PMC text mining. Sharing a sentence is not in itself a finding about the gene and the disease. The quoted sentences say what the papers report.
breast carcinoma (29 papers, 2018 to 2025). "Inhibition of JAK/STAT3 signaling suppresses self-renewal of breast cancer stem cells (BCSCs) and downregulates key lipid metabolic genes such as carnitine palmitoyltransferase 1B (CPT1B), which encodes a rate-limiting enzyme in fatty acid β-oxidation (FAO)." (PMID 41269404, 2025). "In the breast cancer, expression of a variety of lipid metabolic genes, including carnitine palmitoyltransferase 1B (CPT1B), which encodes the key enzyme for fatty acid b-oxidation (FAO) is also blocked by the inhibition of JAK/STAT pathway." (PMID 33588867, 2021). "Wang et al8 have reported in breast cancer that the JAK/STAT3 signaling can facilitate the transcription of CPT1B, thereby promoting FAO and sustaining the proliferation of breast cancer stem cells as well as their chemoresistance." (PMID 41340257, 2025). "Leptin secreted by breast adipocytes has been shown to upregulate CPT1B expression in STAT3-induced breast cancer cells." (PMID 41219902, 2025). "For example, CPT1B mRNA levels are elevated in recurrent breast cancer tissues, and CPT1B expression is elevated in chemotherapy-resistant breast cancer patients." (PMID 38302980, 2024). "As CPT1A and CPT1B are the rate‐limiting enzymes of fatty acid oxidation and play a critical role in maintaining the stemness characteristics of breast cancer, we first checked their levels." (PMID 38627980, 2024). "JAK2/STAT3 signaling pathway takes part in the development of chemoresistance in breast cancer by increasing carnitine palmitoyl transferase 1B (CPT1B) and fatty acid beta-oxidation (FAO)." (PMID 38892394, 2024). "CPT1B plays critical roles in maintaining breast cancer cell stemness and enhancing chemoresistance." (PMID 38783346, 2024). "The association between STAT3-induced CPT1B and chemoresistance in breast cancer cells as well as dysregulated CPT1B expression in bladder cancer cells has also been reported." (PMID 32133293, 2020). "The gene ZAR1 from UPUP-only group has been reported to be hypermethylated and upregulated in neuroblastoma, while CPT1B was upregulated in PCa and breast cancer, in which the gene promotes chemo-resistance." (PMID 31914996, 2020). "Another study identified CPT1B as a downstream target of the JAK/STAT3 pathway in breast cancer." (PMID 35433453, 2022). "Interestingly, clinical data from breast cancer patients revealed higher expression of CPT1B in breast carcinomas compared to healthy tissues, while it was also found elevated in recurrent tumors." (PMID 36497394, 2022). "CPT1B is expressed in muscle, heart, and adipose tissue and CPT1C in neurons, whereas CPT1A is more widely expressed and has been previously implicated as a therapeutic target in breast cancer cells." (PMID 29596410, 2018). "In breast cancer, FABP4 exhibits strong affinity for long-chain fatty acids and enhances lipid uptake and metabolism through CPT1B." (PMID 41219902, 2025). "Certain enzymes involved in β-oxidation, such as α-methylacyl-CoA racemase (AMACR) and carnitine palmitoyl transferase 1B (CPT1B), are specifically upregulated in colorectal, hepatic, and prostate cancers, whereas CPT1A is elevated in breast cancer." (PMID 37373069, 2023). "Since CPT1A, CPT1B, and CPT1C belong to the CPT family, we also compared the clinical relevance of CPT1A, CPT1B, and CPT1C in total breast cancer patients and patients with various subtypes of breast cancer." (PMID 35936710, 2022). "In breast cancer, JAK/STAT3 was found to promote FAO in cancer stem cells via directly binding to the promoter of carnitine palmitoyltransferase 1B (CPT1B) that results in transcriptional activation of a key enzyme needed for FAO." (PMID 34766135, 2021). "Carnitine palmitoyltransferase 1B (CPT1B) exerts rate-controlling-enzyme roles in fatty acids β-oxidation, could be inhibited by inhibiting JAK/STAT3 promoting breast cancer cells to re-sensitize to chemotherapy." (PMID 37221577, 2023).
breast carcinoma (continued). "In recurrent breast carcinomas they described enhanced CPT1B mRNA expression compared to tumours that did not recur." (PMID 35433453, 2022).
Obesity (23 papers, 2014 to 2025). Accumulation of substantial excess body fat. "From those variations CPT1B c.282-18C > T and p.E531K variants were related to obesity." (PMID 27127449, 2016). "In our PCOS model, androgen-induced obesity was associated with the downregulation of lipogenesis markers, increased adipogenesis (higher C/EBPβ activity), and upregulation of CPT1A and CPT1B key thermogenesis and mitochondrial biogenesis markers." (PMID 38987854, 2024). "Compared to selectively bred obesity-resistant rats, the mRNA level of CPT1b was lower in SAT of obesity-prone rat." (PMID 37920803, 2023). "CPT1B and ACACB are genes related to fatty acid oxidation and are associated with obesity and diabetes." (PMID 34702302, 2021). "In addition, downregulation of CPT1b reduced fatty acid metabolism and subsequently resulted in the obesity of rats." (PMID 35953554, 2022). "Moreover, expression of Cpt1b and Ucp2 in skeletal muscle is up-regulated in the klf5-knockout heterozygous mouse, which is resistant to high fat-induced obesity and glucose intolerance." (PMID 33639916, 2021). "A recent study reported that decreased CPT1B expression contributes to fat accumulation in obesity." (PMID 31480195, 2020). "Cpt1bm-/- mice have improved glucose disposal regardless of the amount of dietary fat, indicating that pharmacological inhibition of CPT1b may be an effective means of treating metabolic disorders hallmarked by insulin resistance and obesity." (PMID 29240830, 2017). "CPT1B transports free acyl groups into mitochondria for oxidation, and ADRB3 triggers lipolysis in adipocytes, and their respective polymorphisms E531K and W64R have been identified as indicators of obesity in population studies." (PMID 24905907, 2014). "When we investigated the list of 162 DMRs mapping to annotated loci in further detail we observed other genes with known and potential roles in obesity and related traits (such as PRKCZ, NDUFS2, GATA2, FOXP2, ANGPT2, NCOR2, CPT1B, PTPN6)." (PMID 25651499, 2015). "Browning of WAT has been proposed as a mechanism to combat obesity and its co-morbidities, and browning is typically defined as an increase in the UCP1 mRNA/protein or an increase in other brown adipocyte genes, such as CPT1b and PDRM16." (PMID 37108770, 2023). "In addition, our results demonstrate that restoring FAO, targeting carnitine palmitoyltransferase-1B (CPT-1B) via L-carnitine (its endogenous cofactor), could attenuate obesity-induced AF." (PMID 35955426, 2022).
Insulin resistance (15 papers, 2014 to 2024). Increased resistance towards insulin, that is, diminished effectiveness of insulin in reducing blood glucose levels. "In mice, genetically-induced deficiency or age-associated reduction of skeletal muscle CPT1B expression leads to the development of insulin resistance provoked by a high fat diet challenge." (PMID 37275238, 2023). "We therefore propose that the reduction of CPT1B with age specifically in the skeletal muscle plays a key role to predispose individuals to diet-induced insulin resistance." (PMID 34330275, 2021). "This is the first study using a preclinical mouse model with Cpt1b-specific knockdown to investigate the long-term effects of CPT1b repression on HFD-induced insulin resistance and the underlying metabolic mechanisms." (PMID 25309812, 2014). "We investigated the effects of CPT1b deficiency on HFD-induced insulin resistance using heterozygous CPT1b deficient (Cpt1b+/−) mice compared with Wild Type (WT) mice fed a HFD for a prolonged period of time (7 months)." (PMID 25580367, 2014). "In mice, the age-associated decrease in skeletal muscle CPT1B protein exacerbated insulin resistance induced by a high fat diet, indicating that older mice had reduced metabolic flexibility in response to an obesogenic dietary challenge compared with their younger counterparts." (PMID 37275238, 2023). "Since 3-hydroxybutyryl-carnitine (C4-OH) was increased in the Cpt1b+/− muscle, we speculate that increased acylcarnitines in the skeletal muscle may be one of the factors causing severe insulin resistance of Cpt1b+/− mice." (PMID 25580367, 2014). "Taken together, the current investigation confirmed the beneficial effects of CPT1b repression on diet-induced insulin resistance." (PMID 25309812, 2014). "Our current study using the genetic mouse model with CPT1b deficiency provides specific insights and clarifies the effect of CPT1b deficiency on HFD-induced insulin resistance." (PMID 25309812, 2014). "Previously, we found that Cpt1b+/− mice were protected against HFD-induced insulin resistance in mice with up to 5 months of HFD feeding." (PMID 25580367, 2014). "We found that Cpt1b+/− mice were protected from HFD-induced insulin resistance compared to WT littermates." (PMID 25309812, 2014). "Further studies will be required to identify CPT1b-specific inhibitors, and to confirm the effectiveness and safety of prolonged inhibition of CPT1b in animals and in patients with insulin resistance and type II diabetes." (PMID 25309812, 2014). "In conclusion, the recent pharmaceutical model with oxfenicine inhibition of CPT-1 in mice and our previous Cpt1b+/− genetic mouse model studies support that CPT1b restriction is a good therapeutic approach against diet-induced insulin resistance." (PMID 25580367, 2014). "In the current study, we provide evidence supporting the beneficial effects of CPT1b ablation related fatty acid oxidation restriction against insulin resistance induced by HFD." (PMID 25309812, 2014). "Previously we reported that the Cpt1a+/− mice were resistant against HFD-induced insulin resistance, but showed hepatosteatosis with increased hepatic CPT1b expression." (PMID 25309812, 2014). "Moreover, CPT1B overexpression has been reported to improve HFD-induced insulin resistance in a rat model." (PMID 34330275, 2021). "Strategies that enhance muscle CPT1B activity could, nonetheless, offer the potential to attenuate lipid accumulation and consequently lipid-induced insulin resistance in the elderly." (PMID 34330275, 2021). "However, in the current study we report that Cpt1b+/− mice developed severe insulin resistance after 7 months of HFD feeding." (PMID 25580367, 2014). "It is important to clarify whether a prolonged CPT1b inhibition could eventually lead to insulin resistance due to a potential intramyocellular accumulation of certain lipid intermediates." (PMID 25580367, 2014).
Insulin resistance (continued). "Therefore, CPT1b inhibition appeared to be a potentially promising therapeutic approach against diet-induced insulin resistance and onset of diabetes." (PMID 25580367, 2014). "We showed that partial CPT1b deficiency protected against HFD-induced insulin resistance in mice fed a HFD for up to 5 months without significant accumulation of fatty acid-derived metabolites in skeletal muscle." (PMID 25580367, 2014). "We speculate that there must be a tipping point whereby these accumulated lipid metabolites exceed a threshold, leading to severe insulin resistance between the time points of 5 months and 7 months in Cpt1b+/− mice." (PMID 25580367, 2014). "Therefore, it appears that CPT1b is a better specific CPT1 target for the treatment of insulin resistance." (PMID 25309812, 2014). "Both cases support the concept that decreased intramyocellular acylcarnitine can ameliorate insulin resistance, which is consistent with the significantly increased acylcarnitine level in the muscle of insulin resistant Cpt1b+/−mice after prolonged HFD feeding." (PMID 25580367, 2014). "Strikingly, Cpt1b+/− mice showed severe insulin resistance compared to WT mice." (PMID 25580367, 2014). "Therefore, it is probable that partial CPT1b repression protects mice from HFD-induced insulin resistance by attenuating HFD-induced upregulation of fatty acid oxidation and upregulating glucose oxidation in skeletal muscle." (PMID 25309812, 2014). "It is possible that other lipid intermediates (e.g., diacylglycerol and acyl-CoA) may also be involved in the development of insulin resistance in Cpt1b+/− mice." (PMID 25580367, 2014). "Despite the encouraging support of CPT1b inhibition as a potential therapy for insulin resistance as reported here, many other studies using various CPT1 inhibitors have shown adverse effects due to intramyocellular fatty acid-related metabolites (e.g., DAGs, acylcarnitines, ceramides) accumulation." (PMID 25309812, 2014). "The samples from the carotid sheath showed an enriched expression of genes described to play a role in insulin resistance (PPP1R3E, PRKCQ, PRKCZ, CPT1B, MGEA5, RPS6KB2, OGT; KEGG_PATHWAY hsa04931:Insulin resistance)." (PMID 32661330, 2020). "This fact may explain the downregulation of genes related to β-oxidation (CPT1A, CPT1B, and UCP3) in supplemented calves and may represent a protection mechanism against the development of diet-induced insulin resistance." (PMID 36837780, 2023). "Prolonged FAO inhibition in CPT1b–expressing organs of Cpt1b+/− mice resulted in severe insulin resistance only in skeletal muscle, but not other tested organs." (PMID 25580367, 2014). "However, since etomoxir does not discriminate between CPT1A and CPT1B, it was found that long-term inhibition of CPT1B resulted in increased intracellular lipids and insulin resistance in rats." (PMID 39596847, 2024). "Although bezafibrate also induced GLUT4 and CPT1b expression in skeletal muscle, IRS and PDK4 expression was not similarly effected; this together with the stable adiponectin gene expression and unrectified dyslipidemia explained why insulin resistance was not improved by bezafibrate." (PMID 24759758, 2014).